MMP14 (matrix metallopeptidase 14)
Diseases named in the same sentence as MMP14 in open-access papers (continued):
Sharing a sentence is not in itself a finding about the gene and the disease.
Obesity (20 papers, 2013 to 2025). Accumulation of substantial excess body fat. "In advanced obesity, typically associated with longer disease duration, extensive fibrosis, macrophage infiltration, and overt metabolic dysfunction, persistent MMP-14 overexpression becomes pathogenic." (PMID 41227041, 2025). "This translatability is further underscored by recent data, which identified polymorphisms in the Mmp14 gene that associate with obesity and metabolic disease in human cohorts." (PMID 39282008, 2024). "In humans, genetic variants located near the catalytic domain of MMP14 were associated with obesity traits due to enhanced collagen turnover." (PMID 37445827, 2023). "We therefore generated inducible hepatocyte-specific MMP14-deficient (MMP14LKO mice) mice to test the hypothesis that hepatocyte MMP14 deletion is sufficient to attenuate diet-induced obesity and its complications." (PMID 39282008, 2024). "A variant in the human MMP14 is linked to obesity and diabetes." (PMID 36428776, 2022). "However, how obesity-associated MMP14 expression in adipose tissue contributes to cancer progression remains to be determined." (PMID 36428776, 2022). "Recently, gene polymorphisms in membrane-tethered (MT) 1-MMP (MMP-14) have been linked to human obesity and insulin-resistance characteristics, and knockout of this protease was shown to protect from high-fat diet induced adipose tissue remodeling/expansion in mice." (PMID 23936445, 2013). "ECM modification requires MMPs (MMP-14 namely) which are upregulated in the initial stages of obesity to promote healthy expansion in obesity." (PMID 40696355, 2025). "Regarding the PUFAs, it has been reported that combined EPA-DHA treatment negatively affects leptin and obesity-related membrane-type MT1-MMP (MMP-14) mRNA expression in rabbit subcutaneous ASCs in vitro." (PMID 37235430, 2023). "At later stages of obesity, a high quantity of endotrophin is produced by the MMP14-induced digestion of COL6α3, which has pro-inflammatory and pro-fibrotic actions, contributing to insulin resistance." (PMID 37445827, 2023). "At the early stage of obesity development, MMP14 digests collagen and prevents fibrosis, which in turn promotes the healthy expansion of the tissue." (PMID 36428776, 2022). "Our studies have reported that MMP14 cleaves the COL6A3 chain to generate endotrophin, a bioactive peptide associated with obesity pathogenesis." (PMID 33317052, 2020). "Moreover, in obesity, membrane-bound matrix metalloproteinase 14 (MT1-MMP/MMP14) inhibits GDF15 signaling by blocking GFRAL." (PMID 41234361, 2025). "MMP-14 (MT1-MMP) demonstrates dual, stage-dependent activity in obesity." (PMID 41227041, 2025). "In sum, we have demonstrated an inter-organ and hepatocyte-intrinsic dual inflammatory and metabolic function for MMP14 that is pharmacologically modifiable, and we provide novel agents with which to achieve MMP14 targeting to potentially abate obesity and its complications." (PMID 39282008, 2024). "Recently, the involvement of MMP14 in ECM remodeling during obesity has been unveiled." (PMID 37445827, 2023). "Elevated in vesicles from oleic acid hypertrophied adipocytes are other proteins of interest in relation to adipose tissue and obesity, such as PARK7/DJ-1 and MMP-14." (PMID 32214011, 2020). "Here, we show that MT1-MMP (also known as MMP14), a collagenase highly expressed in AT and further induced in obesity, is co-expressed with DCN in ASC and cleaves DCN to generate ΔDCN." (PMID 33317052, 2020). "In early obesity, characterized by adipose tissue expansion, limited fibrosis, and mild or absent insulin resistance, MMP-14 facilitates ECM degradation and remodeling, promoting healthy adipocyte hypertrophy and angiogenesis." (PMID 41227041, 2025). "In addition to MMP2, our laboratory has demonstrated that MMP14 cleaves the catalytic domain of MMP11, an important regulator of energy metabolism protecting from diet-induced obesity, fatty liver and insulin resistance." (PMID 37445827, 2023).
Obesity (continued). "In summary, our study indicates that DCN lacking GAG is generated by cleavage with MMP14 and suggests that MMP14 induction in obesity is responsible for the accumulation of DCN lacking GAG." (PMID 33317052, 2020). "MMP14 is highly expressed in WAT, in particular in obesity, and regulates WAT remodeling." (PMID 33317052, 2020). "When the effect of obesity was studied, the expression of LAMB1, Serpine1, MMP14, MMP10 appeared to decrease but a general downward trend could be noted." (PMID 33505957, 2020). "Furthermore, matrix metalloproteinase 14 (MMP14), which is highly expressed in the WAT of individuals with obesity, may play an important role in remodeling processes and established role in cancer development." (PMID 39763022, 2025). "However, in two animal models of genetic obesity (ob/ob and db/db) and in a HFD model, while mRNA levels for MMP2, MMP3, MMP12, MMP14, MMP19, and TIMP1 are robustly induced, MMP7 (and MMP3) transcripts are markedly reduced in obese visceral adipose tissue compared to lean tissue." (PMID 37445827, 2023).
sarcoma (17 papers, 2009 to 2026). A usually aggressive malignant neoplasm of the soft tissue or bone. "The expression and function of the membrane-type matrix metalloproteinase MMP14 is closely related to the mesenchymal cell phenotype, and it is highly expressed in most sarcomas." (PMID 31466240, 2019). "In a cohort of various sarcoma types as well as benign soft tissue neoplasms, MMP14 protein expression has been found to be higher in sarcomas than in the benign tissues." (PMID 31466240, 2019). "In other sarcomas, the increased MMP14 expression is a far more common phenomenon than copy number alterations." (PMID 31466240, 2019). "Surprisingly, while MMP14 in the context of cancer has mostly been investigated in epithelial tumors, its role in sarcoma remains relatively unexplored." (PMID 31466240, 2019). "Although several microRNAs have been reported to target MMP14, their activities in sarcoma remain uninvestigated." (PMID 31466240, 2019). "Few clinical studies have investigated the role of MMP14 in rhabdomyosarcoma and Ewing sarcoma, which both express relatively low levels of MMP14 as compared to other types of sarcoma." (PMID 31466240, 2019). "Here, we provide an overview of the function and regulation of MMP14 and we discuss their relationship with clinical and pre-clinical MMP14 data in both adult and childhood sarcomas." (PMID 31466240, 2019). "Thus, a comprehensive understanding of the biology of MMP14 in sarcomas will shed light on the mechanisms controlling the key processes in these diseases." (PMID 31466240, 2019). "Together, these reports establish the tight association between MMP14 and the mesenchymal phenotype, suggesting that MMP14 may also contribute to determining the phenotypical characteristics of sarcomas." (PMID 31466240, 2019). "Moreover, understanding the cell phenotype- and tissue-specific functions of MMP14 in sarcoma will be central to evaluate its potential as a prognostic marker or a therapeutic target." (PMID 31466240, 2019). "This approach identified a pool of sarcoma-specific genes, including many like FAP or MMP14 in UPS which are upregulated in STS compared to almost all normal cell types." (PMID 40814001, 2025). "Amongst sarcomas, PROX1 is highly expressed in rhabdomyosarcoma, which could explain the generally low expression of MMP14 in this sarcoma type." (PMID 31466240, 2019). "On the other hand, the membrane proteins flotillins, which form caeolin-1- and clathrin-independent membrane invaginations, promote MMP14 internalization inducing its recycling to invadopodia and ECM degradation in both high flotillin-expressing carcinoma and sarcoma cells." (PMID 31466240, 2019). "Our data suggest that to improve the likelihood of success, rather than a “one size fits all” pan-sarcoma approach, future trials evaluating this agent should be selectively enriched for the UPS subtype which harbors particularly high levels of MMP14." (PMID 38810090, 2024). "Although mechanistic studies on the preference for sarcoma cells to use the hematogenous over the lymphogenous route, and to metastasize in the lungs, are lacking, the mesenchymal characteristics and the high MMP14 expression of these tumors might explain the intravasation into blood vessels." (PMID 31466240, 2019).
neuroblastoma (16 papers, 2009 to 2023). Neuroblastoma (NB) is the most common solid, extracranial childhood tumor. "Similar MMP-14 targeting has been demonstrated to improve cytoreductive surgery in childhood neuroblastoma by the creation of a FRET nanoprobe conjugated to MMP-14 peptide, in which cleavage of the peptide results in tumor illumination." (PMID 36077371, 2022). "Overexpression of HNF4α can enhance the aggressiveness and angiogenesis of neuroblastoma cells via its direct upregulation of matrix metalloproteinase 14 (MMP-14)." (PMID 31695151, 2020). "Zhang H reported that miR-9 abolished the malignant phenotypes of neuroblastoma cells via targeting matrix metalloproteinase 14 (MMP-14)." (PMID 30795814, 2019). "In neuroblastoma tissues, MMP-14 expression was monitored using immunostaining and correlation to clinical data revealed an association of MMP-14 expression with poor patient survival." (PMID 24670365, 2014). "In addition, hepatocyte nuclear factor 4 alpha exhibits oncogenic activity through directly binding to the MMP-14 promoter and facilitating its transcription in neuroblastoma." (PMID 27259238, 2016). "Membrane-type 1 matrix metalloproteinase (MT1-MMP, MMP-14), an enzyme involved in several steps in tumor progression, has previously been shown to be associated with poor clinical outcome for neuroblastoma." (PMID 19961596, 2009). "We demonstrated that miR-337-3p was under-expressed and inversely correlated with MMP-14 expression in clinical specimens and cell lines of neuroblastoma (NB), the most common extracranial solid tumor in childhood." (PMID 26084291, 2015). "MMP-14 overexpression has also been correlated with aggressiveness and poor outcome in neuroblastoma, and MMP-14 knockdown decreased migration, invasion and angiogenesis in neuroblastoma cells." (PMID 26729169, 2015).
myocardial infarction (15 papers, 2013 to 2025). Gross necrosis of the myocardium, as a result of interruption of the blood supply to the area, as in coronary thrombosis. "Future research will be required to determine why MMP14 plays a positive pro-regenerative role in adult zebrafish and yet appears to exacerbate the damage associated with myocardial infarction in mammals." (PMID 36271843, 2023). "Deficiencies in TIMP-2 activity after myocardial infarction accelerates adverse myocardial remodeling due to enhanced MMP-14 activity." (PMID 23349729, 2013). "We analyzed their published datasets and found that Mmp14 expression was induced 2.98-fold (n = 4 per group, P < 0.001) in endothelial cells in hearts subjected to myocardial infarction compared to sham controls." (PMID 38019918, 2023). "More recently, it has been shown that macrophage-specific deletion of MMP14 in adult mice reduces left ventricular dysfunction following myocardial infarction." (PMID 36271843, 2023). "It has been demonstrated that MMP-14 is upregulated in a particularly harmful macrophage phenotype (MMP14+TIMP3−), which contributes to increased risk for plaque rupture and myocardial infarction." (PMID 34702365, 2021). "For instance, MMP14, a member of the MT-MMP subfamily, has been implicated in acute myocardial infarction." (PMID 32206187, 2020). "Particularly, MMP14 is secreted by cardiomyocytes and fibroblasts after myocardial infarction and participates to myocardial remodeling." (PMID 29367534, 2017). "Indeed, MMP14 heterozygote knockout mice display a marked improvement in survival post myocardial infarction due to reductions in infarct size, left ventricular dilation, and compensatory hypertrophy." (PMID 36271843, 2023). "To gain further insight into MMP14 expression by macrophages, we re-analysed two previously published scRNA-seq datasets from non-regenerating adult mice and regenerating neonatal mice after myocardial infarction." (PMID 36271843, 2023). "In an animal model of myocardial infarction (MI), MMP14 expressed in macrophages induced their release of TGFβ1, which subsequently resulted in activation of SMAD2-mediated EndMT pathways in nearby ECs through paracrine signaling." (PMID 34566697, 2021). "Re-analysis of scRNA-seq data from adult mice and neonates following myocardial infarction showed that, conversely to what we observed in zebrafish, Mmp14-expressing macrophages were not present in the myocardium prior to injury." (PMID 36271843, 2023). "Our work therefore suggests that reducing MMP-14 activity and increasing that of TIMP-3 could be valid therapeutic approaches to reduce plaque rupture and myocardial infarction." (PMID 25301980, 2014). "Interestingly, Mmp14+ macrophages were absent at baseline and 3 days post myocardial infarction in both adult and neonatal mice." (PMID 36271843, 2023). "Therefore reducing MMP-14 activity and increasing that of TIMP-3 could be valid therapeutic approaches to reduce plaque rupture and myocardial infarction." (PMID 25301980, 2014). "In addition, the membrane-type MMP (MT1-MMP/MMP14), which cleaves several ECM proteins, has been highlighted to be of importance in the heart, as a reduction in MT1-MMP improves survival and heart function post myocardial infarction in mice, whilst overexpression lowers survival and function." (PMID 29075197, 2017).
liver fibrosis (14 papers, 2016 to 2025). "Similar to our results, upregulation of MMP2 and MMP14 together with upregulation of TIMP1 has been shown in liver fibrosis." (PMID 38990974, 2024). "The synthesized peptide YJ successfully mimics TSG-6 action, preventing CD44 cleavage by obstructing MMP14 activity in HSCs and alleviating hepatic fibrosis." (PMID 38790021, 2024). "We previously highlighted the use of syndecan-1 as a reliable marker of liver fibrosis, given the involvement of its extra membrane domain in the synthesis of MMPs, particularly MMP-14." (PMID 37109427, 2023). "This was interesting as recently, it was demonstrated that secreted MMP14 is a suitable predictor for MSC potency to reduce liver fibrosis." (PMID 35163683, 2022). "On the other hand, there are few reports on the role of MMP14 in glucose and lipid metabolism, in spite of having been reported to contribute to the improvement of liver fibrosis." (PMID 34361079, 2021). "Yet, the involvement of MMP-14 in the pathogenesis and resolution of liver fibrosis remains so far ambiguous." (PMID 32296422, 2020). "We have previously shown that sinusoidal angiogenesis driven by myeloid cell-derived VEGF along with upregulation of MMP-2 and MMP-14 in sinusoidal endothelial cells is required for the resolution of liver fibrosis." (PMID 28118605, 2017). "Our findings suggest that MMP-14 is mainly responsible for the improvement of liver fibrosis." (PMID 31048740, 2019). "Finally, knockdown experiments revealed that MMP-14 was primarily responsible for the reduction of liver fibrosis." (PMID 31048740, 2019). "In the ALD mouse model, MMP14 at both the RNA and protein levels was upregulated with increased CD44 activity and liver fibrosis." (PMID 38790021, 2024). "TSG-6 binding to CD44 masked the proteolytic cleavage region of CD44 from matrix metalloproteinase 14 (MMP14), blocked CD44ICD generation in HSCs, and suppressed HSC activation and liver fibrosis in ALD mice." (PMID 38790021, 2024). "TSG-6 interacted directly with the catalytic site of MMP14, a proteolytic enzyme that cleaves CD44, inhibited CD44 cleavage to CD44ICD, and reduced HSC activation and liver fibrosis in ALD mice." (PMID 38790021, 2024). "IC-2-engineered MSC sheets reverse established liver fibrosis by augmenting the secretion of activated MMP-1 and MMP-14, particularly MMP-14, although generally considered to be a membrane-bound protein but has been proven to act in a soluble form as well." (PMID 35883127, 2022). "Many of these genes, including COL1A1, LOX, MMP14, TGFB3, TIMP1 and VCAN, are known markers for liver fibrosis." (PMID 34588551, 2021). "However, TSG-6 treatment notably downregulated MMP14 at both the RNA and protein levels, similar to the effect of decreasing CD44 activity and liver fibrosis in the EtOH-treated mice." (PMID 38790021, 2024). "Hence, it is possible that TSG-6 physically inhibits the catalytic activity of MMP14 and protects CD44 cleavage to CD44ICD from MMP14 to reduce HSC activation and liver fibrosis in mice with ALD." (PMID 38790021, 2024). "Parallel studies have also confirmed that MMP14 and ITGB1 are upregulated in hepatic fibrosis, which is gradually reduced with recovery suggesting that their blocking could be a potential anti-inflammatory therapeutic strategy in NASH." (PMID 36077546, 2022). "The expression of membrane-bound MMP-14 by Ly6Chi monocytes and MoMFs was especially intriguing, as most studies emphasize the importance of secreted MMPs like MMP-8,−9,−12, and−13 in reducing liver fibrosis." (PMID 32296422, 2020). "Because we did not detect alterations in scar formation in the macrophage MMP-14 mouse mutants, it is conceivable that collagenolytic activity in scar derives from another enzyme, possibly MMP-13, that is pivotal in this process in liver fibrosis." (PMID 27066886, 2016).
Arthritis (13 papers, 2008 to 2025). Inflammation of a joint. "Mice deficient for MMP14 develop craniofacial dysmorphisms, dwarfism, osteopenia and arthritis due to loss of collagenolytic activity that is essential for modeling skeletal and extraskeletal connective tissues." (PMID 23326364, 2013). "Furthermore, MMP-14 deficiency causes arthritis due to the ablation of collagenolytic activity, which is essential for the modeling of skeletal connective tissues." (PMID 32518385, 2020). "Other identified target genes included MMP13 and MMP14 of the metalloproteinase family, involved in tissue remodeling and cartilage degradation, which are activated in non-pathological post-exercise conditions but can be associated with pathologic processes, including tumor invasion and arthritis." (PMID 37445763, 2023). "MMP14 is one of the MMPs involved in arthritis and activates MMP-2 and 1346." (PMID 40087276, 2025). "MMP14 is involved in extracellular matrix catabolism during normal physiological processes such as embryonic development, reproduction, and tissue remodeling, as well as during disease processes such as arthritis and metastasis of tumors." (PMID 38898429, 2024). "MSCs-Exos carrying miRNA-150-5p significantly down-regulated the concentration of MMP14 and VEGF (vascular endothelial growth factor) which reduced the severity of arthritis." (PMID 32143603, 2020). "Lack of activity of MMP-14 (MT1-MMP) induces dwarfism, osteopenia, arthritis, and connective tissue disease." (PMID 31653893, 2019).